U6 (U6 spliceosomal RNA )
Synonyms: LOC124904108
Gene: Small nuclear RNA gene on chromosome 17 (90,796 to 90,899, reverse strand). Ensembl gene ENSG00000277613.
Gene Ontology:
Molecular function: U4 snRNA binding
Biological process: formation of quadruple SL/U4/U5/U6 snRNP; spliceosomal tri-snRNP complex assembly
Cellular component: U4/U6 x U5 tri-snRNP complex; U6 snRNP
Homologues: Orthologues: macaque U6 (91% identical), pig U6 (84% identical), pig U6 (78% identical), dog U6 (77% identical). Paralogues in human: RNU6-1076P (100% identical), RNU6-1100P (100% identical), RNU6-1118P (100% identical), RNU6-1217P (100% identical), RNU6-355P (100% identical), RNU6-447P (100% identical), RNU6-785P (100% identical), RNU6-791P (100% identical), RNU6-860P (100% identical), U6 (100% identical), RNU6-1054P (99% identical), RNU6-1199P (99% identical), and 1290 more.